CD44 (CD44 molecule (IN blood group))
Diseases named in the same sentence as CD44 in open-access papers (continued):
Sharing a sentence is not in itself a finding about the gene and the disease.
lung carcinoma (continued). "Increasing evidence suggested that differential expression cancer stem cell markers, such as ALDH1, CD133 and CD44, was tightly correlated with the pathological subtypes and tumor development of lung cancer." (PMID 35473511, 2022). "In another study, gefitinib-loaded nanomicelles with conjugation of this CD44 RNA aptamer inhibited spheroid formation of CD133-positive lung cancer cells." (PMID 34976591, 2022). "The mRNA levels of Sp1 and CD44, including CD44s and CD44st, exhibited inverse correlations in the clinical lung cancer cohorts." (PMID 35034634, 2022). "Our results suggest that Auger electron emitters can also eradicate resistant lung cancer CD44+ populations." (PMID 35806135, 2022). "Earlier, we published that IGFBP-3 binds HA through this 18-residue basic motif and blocks HA interactions with its receptor, CD44, reducing viability of A549 human lung cancer cells." (PMID 36428962, 2022). "In the present study, we sort patient-derived lung cancer cells based on their expression of CD44 and show that CD44+ cells are resistant to cisplatin." (PMID 35806135, 2022). "Eight lung cancer specimens collected from lung cancer patients were used to study the protein levels of Sp1 and CD44." (PMID 35034634, 2022). "Samples obtained from lung cancer patients were used to study the mRNA level of CD44 by q-PCR and the protein levels of Sp1 and CD44 by immunoblot and immunohistochemistry." (PMID 35034634, 2022). "Overexpression of GFP-Sp1 decreased the CD44 level, and Sp1 knockdown increased the CD44 level in A549 and H1299 lung cancer cell lines, indicating that Sp1 negatively regulates CD44 expression in lung cancer cells." (PMID 35034634, 2022). "E2 increases RNF4 expression to repress Sp1 levels in premenopausal women with lung cancer, thus decreasing the expression of several miRNAs that can target CD44 and ultimately leading to cancer malignancy." (PMID 35034634, 2022). "A current study found that chemoresistant NSCLC patients had upregulated Notch3 expression, which was related to poor prognosis and had augmented levels of CSC markers, ALDH1A1 and CD44, correlating with Notch3 expression in lung cancer biopsies." (PMID 35053430, 2022). "A study around Kong and coworkers demonstrated that CD44 expression activated and therefore positively correlated with PD-L1 expression in breast and lung cancer." (PMID 35269569, 2022). "Our study also indicated that E2 reduced Sp1 levels to inhibit miRNA expression, in turn enhancing CD44 expression, subsequently resulting in a poor prognosis in women with lung cancer." (PMID 35034634, 2022). "We first examined if CD44 isoform expression in lung cancer MSC was different from that of normal MSCs." (PMID 35707369, 2022). "Many studies have found that lung cancer cells with a high expression of the CD44 subset have higher tumorigenic ability, tumor sphere formation ability, and migration characteristics than those with low expressions of CD44." (PMID 36613925, 2022). "We identified a CD44/PAK1/AKT signaling axis as a commonly occurring resistance mechanism to FGFR1 inhibition in lung cancer." (PMID 35853934, 2022). "In lung cancer, studies have shown that CD44 expression is higher in NSCLC than in SCLC, and the highest expression level was observed in lung squamous cell carcinoma." (PMID 35719973, 2022). "Cluster of differentiation 44 (CD44) is a cell surface glycoprotein overexpressed in varieties of solid tumors including pancreatic, breast, ovary, brain, and lung cancers." (PMID 35431911, 2021). "Double-positive CD133+/CD44+ primary AC-derived lung cancer cells revealed higher colony formation units than CD133-/CD44- ones." (PMID 33925297, 2021).
lung carcinoma (continued). "We overexpressed CD44 in lung cancer cell lines with low expression of CD44 and knocked down CD44 expression in lung cancer cell lines with high CD44 expression." (PMID 34439211, 2021). "In this study, we investigated the role of CD44 stemness marker in lung cancer using in vitro and clinical studies." (PMID 34439211, 2021). "The HA-DOPE conjugate was also used for the preparation of lipoplexes for the delivery of anti-telomerase siRNA to CD44+ lung-cancer cells." (PMID 34683830, 2021). "Next, we used overexpression and knockdown approaches to investigate the effects of CD44 on lung cancer cell migration and invasion abilities." (PMID 34439211, 2021). "We present here a TRAF4/6-dependent mechanism for how CD44 is cleaved, and demonstrate that the cleavage occurs at increased rate in stem-like A549 lung cancer cells grown in spheres." (PMID 33804427, 2021). "CD44 normally expressed in embryonic cells, bone marrow, and connective tissue, CD44 is abnormally extensively expressed in pancreatic, breast, and lung cancers, especially in stem cell subpopulations." (PMID 33672756, 2021). "In summary, we imply that Bach1 demonstrates great potential for the treatment of lung cancer metastasis and recurrence via activating CD44 and MPAK signaling." (PMID 34949193, 2021). "In agreement with previous work, our in vitro and in vivo results show that CD44 plays a role in the metastasis of lung cancer cells." (PMID 34439211, 2021). "Through the CD44/NFκB pathway, OPN-a binds to, stabilises and activates CD44 expression, which in turn enhances lung cancer cell growth." (PMID 34944493, 2021). "We found that CD44 promotes the migration and invasion abilities of lung cancer cells through ERK–ZEB1 signaling." (PMID 34439211, 2021). "Basic studies have indicated that the HA/CD44 axis can lead to tumor cell migration that can promote metastasis formation in various tumors, which can lead to tumor cell migration in lung cancer." (PMID 35154001, 2021). "In this study, we investigated the role of CD44 in lung cancer metastasis by using clinical studies as well as in vitro and in vivo studies." (PMID 34439211, 2021). "Further, Wang and colleagues depicted that IL6 pretreatment of CD133+/CD44+ cells assisted in entering into the cell cycle in quiescent lung cancer stem cells and significantly increased chemosensitivity." (PMID 33925297, 2021). "Since the ERK pathway has been reported to promote epithelial to mesenchymal transition (EMT), we further examined the expression of EMT-related proteins in lung cancer cells with CD44 knockdown and overexpression." (PMID 34439211, 2021). "EMT marker analysis revealed that ZEB1 expression was increased, and Claudin-1 expression was decreased in CD44-overexpressing lung cancer cells." (PMID 34439211, 2021). "CD44 overexpression significantly increased migration and invasion abilities of lung cancer cells through CD44-induced ERK phosphorylation, ZEB1 upregulation, and Claudin-1 downregulation." (PMID 34439211, 2021). "This study also revealed several up-regulated genes associated with lung cancer such as TOP2A and MKI67, and with tumor metastasis such as CDH11 and CD44." (PMID 34492061, 2021). "We detected CD133, CD44, and Oct-4, which are vital markers of lung cancer stem cells, by Western blot." (PMID 34976785, 2021). "Herein, we report that high CD44 expression promotes lung cancer cell metastasis in vitro and in vivo through activation of ERK–ZEB1 signaling." (PMID 34439211, 2021). "Our in vivo results revealed that lung metastasis rate was lower in mice injected with CD44-knockdowned lung cancer cells, although the p-value was only borderline significant from statistical analysis." (PMID 34439211, 2021).
lung carcinoma (continued). "The tumor-targeting ability was improved by layer-by-layer assembly of the cationic lactoferrin and the anionic hyaluronic acid, which target the CD44 and lactoferrin receptors overexpressed by lung cancer cells." (PMID 31973051, 2020). "In summary, our research is an important starting point for further studies that are needed to better define the CD44+/EPCAM+ superficial marker highlighting lung cancer stem cells." (PMID 32391123, 2020). "CD133/CD44-NM-Gef displayed greater therapeutic efficacy against lung cancer-initiating cells which is crucial for improving therapeutic effects." (PMID 32998391, 2020). "The interaction of HA fragments with CD44 in the ECM weakened the anti-tumor ability of cytotoxic T lymphocytes by reducing Fas-mediated apoptosis in lung cancer." (PMID 32825245, 2020). "Recently, we found that IGFBP-3 binds HA through residues 215–232 in the C-terminal region of the protein (215-KKGFYKKKQCRPSKGRKR-232) and blocks its interactions with CD44, reducing cell viability of A549 human lung cancer cells." (PMID 32193421, 2020). "Serglycin is an intracellular PG that aggregates with CD44 to promote lung cancer cell migration by triggering the CD44/NF-κB/CLDN1 and CD44/Rho/Src/FAK axes." (PMID 32825245, 2020). "Due to the overexpression of CD44 and lactoferrin receptors on the surface of lung cancer cells, these nanocomplexes were shown to have favored cell recognition, mediated by chondroitin sulfate and lactoferrin content, respectively." (PMID 31973051, 2020). "The expression of the lung cancer stem cell marker CD44 and TGF-β ligand TGFB1 was also reduced by the depletion of TNFAIP6 in active PLK1-expressing cells." (PMID 31548612, 2020). "CD44 was overexpressed in A549-cisplatin resistant lung cancer cells but EGCG treatment exerted repressive effects on CD44 levels by enhancing miR-485-mediated targeting of CD44." (PMID 32290543, 2020). "Previously, we found that IGFBP‐3 binds HA via amino acid residues 215–232 in the C‐terminal region of the protein (215‐KKGFYKKKQCRPSKGRKR‐232), blocking HA interactions with CD44 and reducing viability of A549 human lung cancer cells." (PMID 32592613, 2020). "Lung cancer cells expressing CD44 are enriched for stem‐like properties, and CD44‐positive cells show a higher level of expression for pluripotency markers (Oct‐4, Sox‐2) and increased resistance to cisplatin." (PMID 32991066, 2020). "FOXM1 and key proteins of the Wnt/β-catenin pathway were upregulated in CD133 + CD44+ lung cancer stem cells (LCSCs) compared with that in CD133 + CD44- cells." (PMID 30992007, 2019). "SPP1 binds to CD44 and integrin receptor in the lung cancer cell and activates the FAK/PI3K/AKT pathway which induces the secretion of vascular endothelial growth factor (VEGF) resulting in increased cell survival, cell proliferation and tumor metastasis." (PMID 31681566, 2019). "In lung cancer, CSCs can be characterized by an increase in stem cell transcription factors and cellular surface markers, such as CD44 and CD133." (PMID 30754694, 2019). "The relationship between PAX6 expression and the expression of lung cancer stem cell biomarkers including CD44, CD133, and ALCAM31 was detected by western blot and immunofluorescence analyses." (PMID 31024010, 2019). "CD44+/CD90+ stem-like cells were identified in above cisplatin-resistant lung cancers (termed as cisplatin-resistant lung cancer stem-like cells, (Cr-LCSCs)) and stained with PKH26 dye which was used to define the self-renewal pattern." (PMID 31781681, 2019). "CD44 also contributes to the activation of Kras-mediated signaling through MAPK pathway in lung cancer cell line models." (PMID 29747682, 2018).
lung carcinoma (continued). "What’s more, CXCR7/TGFβ1 coexpression was positively correlated with the expression of CD44, a cancer stem cell marker promoting lymph node metastasis in lung cancer." (PMID 30574021, 2018). "The micellar internalization into lung cancer cells was through CD44 and clathrin dual-mediated endocytosis." (PMID 29747682, 2018). "CD44 has also been dubbed as a putative cancer stem cell (CSC) in lung cancers and MPM because of its significant influence on disease progression and negative treatment outcome." (PMID 28403901, 2017). "Taken together, these findings indicate that HA is an important targeted delivery ligand for polymer nanoparticle-mediated gene delivery toward CD44-expressing lung cancers." (PMID 28290155, 2017). "The relative expression levels of CD44, cyclin-D1, and c-myc were significantly decreased by atranorin treatment in lung cancer cells." (PMID 28811522, 2017). "MiR-410 elevated the expressions of stem cells markers such as Oct4, Sox2, Nanog, CXCR4 and putative lung cancer stem cells surface marker CD44 and CD166." (PMID 28076327, 2017). "We have shown the ALDH+/CD44+ fraction of lung cancer cells, despite being the smallest subset, demonstrates the highest tumorigenic capacity compared to counterpart subsets." (PMID 28737489, 2017). "SLC39A4 expression was significantly correlated with the expression of the lung cancer stem cell biomarkers CD44 and CD13323 (Z = 7.11, P < 0.00001)." (PMID 28775359, 2017). "We demonstrate miR-410 increases the levels of stem cells marker Sox2, Oct4, Nanog, CXCR4 as well as lung cancer stem cells surface marker CD44 and CD166." (PMID 28076327, 2017). "Assessment of the expression of CD44 in 12 human lung cancer cell lines and 23 paraffin-embedded lung cancers showed that CD44s is the predominant isoform." (PMID 28460475, 2017). "Previous studies on several types of human cancers – including breast, brain and lung cancers – have identified a group of cells called CD44+/CD24- cells that seem to be more aggressive and resistant to therapy than other cancer cells." (PMID 28092266, 2017). "Transferrin receptor, FRA, EGFR, integrins, and CD44 are common receptors that have been explored for targeted nanoparticle-based gene delivery in lung cancer." (PMID 28290155, 2017). "Various receptors, including folate receptor alpha (FRA), epidermal growth factor receptor (EGFR), integrins, CD44, and transferrin, are known to be overexpressed in lung cancer cells." (PMID 28290155, 2017). "Relative expression levels of CD44, cyclin D1, and c-myc were significantly decreased by (+)-usnic acid treatment in lung cancer cells to different extents." (PMID 26751081, 2016). "The aim of this study was to investigate the effects of ITGβ3 and CD44, two important growth-enhancing molecules in lung cancer cells, on the regulatory role of OPN-a in lung cancer cell growth." (PMID 27487131, 2016). "It has been reported that the CD44 (high) tumorigenic subsets in lung cancer biospecimens are enriched for low miR-34a expression." (PMID 28074102, 2016). "We determined mRNA expression levels of the stemness genes NANOG and Oct4B, and also of the putative lung cancer stem cell markers CD44 and CD133." (PMID 26895954, 2016). "Recent studies have demonstrated that several markers of cancer stem cells in lung cancer, such as CD44, CD133 and ALDH1, are closely correlated with vimentin expression and the EMT in lung cancer." (PMID 27657690, 2016). "Levels of ITGβ3 and CD44 specifically determine the effects of OPN-a on growth in lung cancer cells." (PMID 27487131, 2016). "To identify the subpopulation of putative CSCs in cancer cell lines, we investigated the expression of three stem cell surface markers (CD166, CD44, and EpCAM) that previously were described as prominent CSCs markers in lung cancer." (PMID 25881239, 2015).
lung carcinoma (continued). "Anti-CD44 antibodies have been exploited for targeted delivery of anti-cancer agents to several types of carcinomas, including breast, colorectal, and lung cancers." (PMID 25909172, 2015). "Cytotoxicity, uptake and activity of both PLGA/PEI/HA and PLGA/PEI NPs were evaluated in CD44(+) (A549) and CD44(−) (Calu-3) lung cancer cells." (PMID 25888948, 2015). "PEI and HA/PEI-decorated NPs were tested for trafficking and activity in CD44(+) and CD44(−) lung cancer cells and potential contribute of HA targeting was highlighted." (PMID 25888948, 2015). "We observed that lung cancer oncospheres contained higher percentages of CD133+ or CD44+ cells than did parental cells." (PMID 25965829, 2015). "HA-coated NPs with excellent stability in complex media and demonstrating unprecedented uptake and activity in CD44-overexpressing lung cancer cells as compared with free drug were obtained." (PMID 25888948, 2015). "As a single marker, CD44 is currently considered as a putative CSC indicator in human carcinomas including cancer of the lung." (PMID 24884875, 2014). "Recent studies also showed that tumor initiating cells with high CD44 expression maintained lung cancer tumorigenicity and drug resistance." (PMID 24519909, 2014). "Analyses in multiple established and patient-derived lung cancer cells well demonstrated that subpopulation of ALDH(hi)CD44(hi) cells showed self-renewal, clonogenicity, highly tumorigenic, high invasion capacities, and resistance to chemotherapy." (PMID 25477004, 2014). "In accordance, clinical lung cancers containing a higher abundance of ALDH and CD44-coexpressing cells was associated with lower recurrence-free survival." (PMID 24091605, 2013). "CD133+ and CD44+ cells are reported to represent “cancer stem cells” in lung carcinomas, which have also been shown to express Oct4 and/or nestin." (PMID 24160469, 2013). "In lung cancer, the common stem-cell-associated markers include Bmi1, CD133, CD44, Sox2, OCT4 and so on." (PMID 23683495, 2013). "We have previously demonstrated lung cancer cells with high CD44 expression were enriched for stem cell-like properties." (PMID 24091605, 2013). "Recently, it has been reported that CD44 is a marker in lung cancer cell lines that define a subpopulation of tumor initiating cells." (PMID 23738757, 2013). "With the exception of OCT4, other markers Bmi1, CD133, CD44, Sox2, Nanog and Msi2 mRNA and protein were abundantly expressed in lung cancer." (PMID 23683495, 2013). "Our previous study detected intratumoral heterogeneity in advance stage of lung cancer by surface marker analysis, immunohistochemistry (CD44, ALDH, cMET, MDRI) and FACS (CD44, ALDH, cMET, CD166, MDR-1, uPAR)." (PMID 24019906, 2013). "Nanog therefore possessed high diagnostic value, however, CD44, Bmi1 and CD133 showed poor diagnostic value in lung cancer." (PMID 23683495, 2013). "The expression of the antigen CD44 was only positive in some single cells in the LC-42 cell line while it was broadly expressed in the lung cancer cell lines EKVX, SELS and HTB-182." (PMID 23738757, 2013). "The ALDH/CD44 co-expression profiles of 11 lung cancer cell lines including PDCL and drug-induced resistant cells were analyzed by flow cytometry." (PMID 24091605, 2013). "In a recent study on metastatic lung cancers in malignant pleural effusion, CD44 was also reported as a possible stem cell marker but the characterization of stem cell-like properties was based on in vitro molecular analysis and cellular expansion only." (PMID 21124918, 2010). "Overall, our results demonstrated that stem cell-like properties are enriched in CD44-expressing subpopulations of some lung cancer cell lines." (PMID 21124918, 2010). "Moreover, Au/HA NP internalization strongly downregulated CD44 expression in lung cancer cells, confirming CD44-mediated internalization." (PMID 41551982, 2026).